INS (insulin)
Diseases named in the same sentence as INS in open-access papers (continued):
Sharing a sentence is not in itself a finding about the gene and the disease.
Insulin resistance (continued). "We noticed that baseline vitamin D was related mainly to fasting insulin, insulin resistance indices, HDL-C and uric acid, whereas baseline chemerin was positively associated with insulin secretion after glucose intake in OGTT and ALT activity in the study group." (PMID 37152969, 2023). "Moreover, a higher total fibre intake was linked to a lower intake of total calories, including saturated fat, which is a known contributing factor to insulin resistance and an insulin antagonist." (PMID 36593443, 2023). "Exercise-enhanced insulin signaling may be crucial in PD to counter the detrimental downstream effects of insulin resistance, such as neuroinflammation, mitochondrial dysfunction, and oxidative stress and a more severe PD phenotype." (PMID 37746149, 2023). "On the other hand, there is an association between insulin resistance and increased levels of plasminogen activator inhibitor-1 (PAI-1, which is a fibrinolytic inhibitor), and insulin and lipoproteins stimulate higher production of PAI-1 by liver and endothelial cells." (PMID 37142990, 2023). "At the level of insulin-dependent cells, insulin resistance occurs." (PMID 37372020, 2023). "Consistent with the impaired insulin action observed in individuals drinking a large amount of alcohol, experimental animals with chronic alcohol intake develop glucose intolerance and/or insulin resistance." (PMID 36979389, 2023). "Before the diagnosis of type 2 DM, insulin resistance may last several years, thus increasing insulin and glucose levels." (PMID 38288476, 2023). "Lastly, the availability of TyG-related indicators for assessing insulin resistance is based on routine clinical care, eliminating the need for specific insulin testing or HIEC, thus making it a readily accessible and cost-effective biomarker with potential clinical applications." (PMID 38179048, 2023). "The DASH diet has been proved to improve insulin resistance and increase insulin sensitivity significantly, and thus may have favourable effects on uric acid excretion." (PMID 36991418, 2023). "In addition, it is recommended that the insulin tolerance test and homeostatic model assessment of insulin resistance (HOMA-IR) should be closely monitored as part of the management of osteoporosis and its related fracture." (PMID 37569816, 2023). "In a state of insulin resistance, the insulin concentration increases." (PMID 37238649, 2023). "In addition, roflumilast therapy rescued the reduced Akt phosphorylation to insulin stimulation in different tissues (liver, fat and skeletal muscle), which revealed severe insulin resistance." (PMID 37072403, 2023). "Fasting insulin and insulin resistance are closely related, which may partly explain why the lean subjects in this study had lower levels of fasting insulin." (PMID 37447183, 2023). "In summary, TNFα is an inflammatory cytokine produced by monocytes and macrophages, and it is involved in the development of insulin resistance by impairing insulin signaling in the WAT and muscles, with visceral fat obesity being a significant site of its production in individuals with obesity." (PMID 37755259, 2023). "Additionally, the KSPAPN cohort displayed insulin resistance upon exposure during an insulin tolerance test (ITT)." (PMID 37848446, 2023). "Cardiac lipotoxicity could lead to insulin resistance since toxic FA metabolites have the ability to impair myocardial insulin signaling." (PMID 37512552, 2023). "Namely, the most pronounced (negative) associations were identified between fasting insulin levels (and accordingly, between estimators of insulin resistance and β -cell function) and various N-glycan structures bearing bisecting GlcNAc." (PMID 37079606, 2023). "Furthermore, the administration of parenteral nutrition is known to have major side effects like hepatic steatosis, insulin resistance, and changes in insulin secretion, which is why we decided to test this approach in our research." (PMID 37144278, 2023).
Insulin resistance (continued). "We first showed that candesartan and azilsartan could alleviate insulin resistance in PA-treated HepG2 cells by fully restoring the impaired insulin-stimulated phosphorylation of AKT and its downstream substrates GSK3β, AS160, FOXO1, and FOXO3." (PMID 37121975, 2023). "This might be attributed to the fact that type 2 diabetes pathogenesis, apart from insulin resistance, also involves defects of insulin-producing β-cells, responsible for decreased insulin production and secretion." (PMID 37079606, 2023). "In addition, we detected a negative correlation between AIP and vitamin D levels, and a positive correlation with BMI, insulin resistance, and insulin levels." (PMID 37189890, 2023). "However, when challenged with a HFD, male Mboat7ASKO mice had an unexpected increase in blood glucose levels, whereas HFD fed Mboat7flox/flox control mice maintained glucose levels after an insulin challenge indicating clear HFD-induced insulin resistance." (PMID 36806709, 2023). "An insulin tolerance test confirmed that he had insulin resistance." (PMID 37042492, 2023). "Similarly, over-nutrition, obesity and obesity-induced insulin resistance challenge the beta cells, overwhelming their capacity to properly handle insulin production." (PMID 37079135, 2023). "The most common form of this disease in adults is type 2 diabetes, which begins with insulin resistance and may progress to a low insulin level." (PMID 36830968, 2023). "In addition, compared with that in the control mice, we found that M92KO reduced insulin resistance in the diabetic mice, as shown by decreased fasting and refed glucose levels, as well as, fasting insulin levels in the serum." (PMID 37985354, 2023). "The pathogenesis of T2DM is complex and affected by various factors, but insulin resistance is one of the main pathophysiological characteristics which occurs when target organs’ exerted physiological effects become less sensitive to circulating insulin." (PMID 37834276, 2023). "In insulin resistance, insulin is ineffective and, therefore, initially prompts an increase in insulin production to reduce rising glucose levels, but over time a state of relatively inadequate production of insulin can develop." (PMID 37240813, 2023). "Obesity and T2D mellitus are commonly seen in subjects with NAFLD and it is well appreciated that excessive accumulation of lipids (i.e., “lipotoxicity) in the liver, skeletal muscle, and pancreatic beta cells can drive the overproduction of insulin and insulin resistance in target tissues." (PMID 36806709, 2023). "Recently, a plethora of studies have indicated that natural products possessing mild pharmaceutical properties can significantly augment insulin sensitivity, suggesting that natural products may be a new strategy for the treatment of insulin resistance." (PMID 38053837, 2023). "Sympathetically mediated vasoconstriction may also functionally antagonize insulin-dependent glycaemic control via reductions in tissue blood flow, contributing to the development of insulin-resistance." (PMID 37153459, 2023). "In addition, resistin secreted by fat cells can inhibit insulin signaling, leading to insulin resistance and the development of T2DM." (PMID 37560059, 2023). "Insulin resistance (IR), characterized by reduced responsiveness of peripheral tissues to insulin, represents a pivotal pathophysiological phenotype in metabolic syndrome, such as hypertension, dyslipidemia, nonalcoholic fatty liver disease (NAFLD), and type 2 diabetes (T2D; Beale, 2013)." (PMID 38107110, 2023). "s-PROK1 was analysed using ELISA at gestational week 19 and related to pregnancy complications, fasting insulin levels, homoeostatic model assessment for insulin resistance (HOMA-IR), testosterone, or androstenedione levels, metformin use, PCOS phenotype and hyperandrogenism." (PMID 37989369, 2023).
Insulin resistance (continued). "Upon conducting miRNA-mediated KEGG pathway analysis, several pathways including the prolactin signal pathway, insulin resistance, autophagy, the insulin-signaling pathway and the FoxO-signaling pathway were found to be significantly enriched in the calf affected by fat necrosis." (PMID 37443947, 2023). "KD feeding induced decreased GLUT4 expression and reduced muscle glucose uptake, reduced α-and β-cell mass and insufficient insulin, and changes in gut microbiota and metabolites may contribute to glucose intolerance and insulin resistance." (PMID 37049471, 2023). "The recognition of insulin resistance as a key factor in PCOS pathogenesis may facilitate the development of targeted therapeutic interventions aimed at improving insulin sensitivity." (PMID 37480140, 2023). "Since insulin activates LPL, a ‘relative’ insulin deficit and/or insulin resistance in type 2 diabetes may be the cause of decreased LPL activity." (PMID 38303975, 2023). "The ADT & Metabolism Study was designed to address these knowledge gaps, as the elucidation of the predominant site of insulin resistance will allow prevention strategies and the use of targeted, tissue-specific insulin-sensitizing agents in patients undergoing ADT." (PMID 36763576, 2023). "Furthermore, increased insulin levels and insulin resistance amplify androgen synthesis from both adrenals and theca cells of the ovary." (PMID 37047265, 2023). "The results showed that the ethanol extracts could significantly regulate blood glucose levels, glycosylated hemoglobin, blood lipids, insulin, and insulin resistance, while also restoring endogenous oxidative stress." (PMID 37764863, 2023). "Furthermore, significant decreases were observed in fasting blood glucose, insulin, homeostatic model of assessment for insulin resistance, free testosterone index, and follicle-stimulating hormone / luteinizing hormone ratio in both groups (P < 0.05)." (PMID 37968684, 2023). "The assignment of this variant to the Hyper Insulin cluster suggests that carriers also have increased insulin resistance, possibly due to a negative feedback loop resulting in increased pituitary secretion of growth hormone." (PMID 37886436, 2023). "In our model, a significant decrease in glycemia was observed in the group fed the SDC diet supplemented with HMB, Lys, and Arg, together with a significantly lower insulin resistance index and a concomitant and significant increase in the insulin sensitivity index." (PMID 38004100, 2023). "Based on the observations, we propose STK38 increase the expression of some inflammatory cytokines via TBK1 signaling pathways, both of which are involved in the pathogenesis of hepatic as well systemic insulin resistance by interfering with insulin signaling and action." (PMID 37028764, 2023). "Indeed, early insulin resistance induces a compensatory response in which insulin production and secretion is enhanced in part due to β-cell hyperplasia." (PMID 37941908, 2023). "Likewise, insulin resistance indexed to ketogenesis (i.e., ketogenesis × insulin) was generally correlated with DNL." (PMID 36928190, 2023). "Additionally, it disrupts the insulin signaling pathway, thus contributing to the development of insulin resistance." (PMID 37375718, 2023). "In addition, our enkephalin knockout mice demonstrated impaired insulin sensitivity during the insulin tolerance test, indicating elevated glucose levels are possibly due to the development of peripheral insulin resistance." (PMID 36979650, 2023). "It should be noted that dietary insulin indices are related to insulin resistance." (PMID 36617570, 2023). "Eccentric exercise could modify the background mechanisms, e.g., increased serum sensitivity, antioxidant capacity, GLUT4 expression, improved lipid profile, decreased insulin resistance, and serum insulin content." (PMID 37775653, 2023).
Insulin resistance (continued). "Our previous study showed that BBR could ameliorate insulin resistance in mice by reducing inflammation and promoting the expression of insulin signaling GLUT4." (PMID 36838862, 2023). "However, immunostaining results from TG mice revealed a negative association between BRSK2 expression levels and the remaining insulin levels, indicating that single β-cell hypersecretion contributes to hyperinsulinemia-induced insulin resistance." (PMID 37188647, 2023). "On the one hand, the activation of the AGEs/RAGE axis initiates intracellular signaling pathways that result in heightened serine phosphorylation and degradation of IRS-1, consequently obstructing the insulin signaling pathway and leading to insulin resistance." (PMID 38260171, 2023). "Likewise, psychological measures of insulin-specific beliefs, often labelled ‘psychological insulin resistance’, are more common in insulin naïve cohorts." (PMID 37237318, 2023). "The pathophysiology of T2DM is characterized by impaired insulin secretion and insulin resistance." (PMID 37915365, 2023). "In this review, we highlight insights from recent unbiased phosphoproteomics studies, which have enabled a comprehensive examination of insulin signalling and have transformed our perspective on how signalling changes may contribute to insulin resistance." (PMID 37248992, 2023). "Their mechanism of action mainly involves improved insulin sensitivity and insulin resistance, inhibited activity of alpha-glucosidase, antioxidant activity, anti-inflammatory, regulation of gut microbiota and activating of peroxisome proliferator-activated receptor-γ." (PMID 38099180, 2023). "In obese/overweight people, increased levels of FGF21 were evident and were correlated with triglycerides, insulin concentration, and insulin resistance, suggesting that FGF21 may serve as a biomarker and early indicator of MASLD severity and progression." (PMID 37998747, 2023). "Furthermore, reduction in exogenous carbohydrate consumption induces lower insulin production, with improvement in hyperinsulinism and insulin resistance, metabolic alterations commonly observed in infertile women." (PMID 37405618, 2023). "Insulin resistance is typical with a state when plasma insulin is at a normal range; however, target tissues cannot exert a physiological response of glucose-lowering, implicating the inhibition of gluconeogenesis, lipolysis, cellular glucose uptake, and glyconeogenesis." (PMID 37664840, 2023). "However, dopamine D2/3 receptor inhibition at the ventral striatum results in diminished insulin sensitivity and decreased mesolimbic dopamine activity leads to insulin resistance." (PMID 36993818, 2023). "In general, the maternal body is regulated by several hormones to maintain the state of insulin resistance during pregnancy, while increased insulin secretion promotes the expression of GLUT in the foetal placental unit to provide adequate glucose and energy for the foetus." (PMID 37355665, 2023). "High plasma levels may be an accompanying effect of insulin resistance and hyperglycemia because research has shown that its hepatic biosynthesis is suppressed by insulin and increased by high glucose concentrations." (PMID 37895024, 2023). "In addition, they described, in the aSyn knock-out mice model, alterations in glucose and insulin responses during diet-induced insulin resistance, and the development of severe insulin resistance after feeding with a high-fat diet." (PMID 37627328, 2023). "Monogenic insulin resistance (IR) includes lipodystrophy and disorders of insulin signalling." (PMID 37794082, 2023). "Studies also suggest that drugs that increase insulin sensitivity may play an important role in the treatment of classic depression, especially in patients with confirmed insulin resistance." (PMID 37892657, 2023). "Reduced demand for insulin is a benefit of resveratrol-induced reduction in insulin resistance." (PMID 37241737, 2023).
Insulin resistance (continued). "Finally, we discuss the recent applications including the diseases related to insulin resistance (obesity, cardiovascular disease, Alzheimer’s disease, and cancer) and the potential treatment of those based on insulin resistance mechanisms." (PMID 37664840, 2023). "Our findings indicate that Aβ may promote peripheral insulin resistance in human by directly impairing insulin signaling in liver and skeletal muscle." (PMID 37538787, 2023). "Moreover, several genetic polymorphisms in the SELENOS gene were demonstrated to be related to T2DM, serum insulin levels, blood glucose levels, and the homeostasis model assessment of insulin resistance." (PMID 37895024, 2023). "Limited evidence from in vitro and in vivo models of insulin resistance indicate that RA may potentially be used to improve insulin sensitivity." (PMID 36982168, 2023). "In addition, compared with LC diet-fed group, HF diet-fed mice showed insulin resistance and glucose intolerance, which were supported by increased blood insulin and glucose levels, homeostasis model assessment-insulin resistance (HOMA-IR) (P < 0.05)." (PMID 36810115, 2023). "Accordingly, it can be assumed that disturbances in the insulin signaling pathway, in particular insulin resistance, may be present in various organs and cells and determine a similar pathology of metabolic regulation in various diseases." (PMID 37833898, 2023). "On the other hand, type 2 diabetes is characterized by insulin resistance, i.e., the inability of insulin-sensitive tissues to respond appropriately to insulin, and may occur due to obesity, hypertension, and dyslipidemia." (PMID 37836872, 2023). "In individuals with insulin resistance, alpha cells may become less responsive to the inhibitory effects of insulin." (PMID 37409229, 2023). "There is evidence that insulin resistance is an early finding in people diagnosed with CKD, and kidney dysfunction seems to be associated per se with defective insulin-signaling pathway, since insulin resistance is a frequent abnormality in CKD regardless of its etiology." (PMID 37525273, 2023). "However, abnormal glucose metabolism (decreased insulin secretion or insulin resistance) will lead to weakened liver cells’ ability to metabolize fat, resulting in increased ectopic fat deposition." (PMID 36875489, 2023). "Thus, the stimulation of peroxynitrite catalysis attenuates HFD-induced insulin resistance in mice by restoring insulin signaling and insulin-stimulated glucose uptake in skeletal muscle tissue." (PMID 37372002, 2023). "In addition, the combination of exenatide and metformin has been reported to have the potential in enhancing certain adipocytokine levels, improving insulin sensitivity in T2D patients, and reducing insulin resistance." (PMID 38179301, 2023). "The insulin tolerance test further informed us of the degree of insulin resistance in mice." (PMID 38004234, 2023). "Additionally, improvement in insulin sensitivity was dependent on the decrease in the total insulin secretion, thus showing that insulin resistance poses less stress on the β-cells and proving that insulin sensitivity and secretion are highly related." (PMID 37362539, 2023). "Excess iron can directly affect insulin synthesis/secretion and enhance oxidation of free fatty acids, in turn decreasing glucose utilisation in muscles and promoting gluconeogenesis in the liver, ultimately leading to insulin resistance." (PMID 37325792, 2023). "Therefore, PC-derived exosomal miRNAs were found to be capable of inducing the insulin resistance of skeletal muscle cells through insulin and PI3K/Akt/FoxO1 signalling pathways." (PMID 37373351, 2023). "Obesity could result in increased insulin secretion pursuing to neutralize rising insulin resistance." (PMID 37476884, 2023).